ENSG00000303840 (novel transcript)
Gene: Long non-coding RNA gene on chromosome 19 (4,723,905 to 4,725,530, forward strand). Ensembl gene ENSG00000303840.
Gene Ontology:
Molecular function: triplet codon-amino acid adaptor activity
Biological process: translation